CTLA4 (cytotoxic T-lymphocyte associated protein 4)
Diseases named in the same sentence as CTLA4 in open-access papers (continued):
Sharing a sentence is not in itself a finding about the gene and the disease.
uveitis (continued). "As part of a subgroup analysis on the different monotherapy treatment regimes, we also found that the class of anti-PD-1 and anti-CTLA-4 had elevated hazard ratios associated with uveitis development compared to their non-ICI comparators." (PMID 38264654, 2023). "Among recipients of the ICI monotherapy regimens, the class of anti-PD-1 (HR:1.98 [CI: 1.65-2.37]), and anti-CTLA-4 (HR:5.86 [CI:1.99-17.24]) showed elevated hazard ratios associated with uveitis development compared to their non-ICI comparators." (PMID 38264654, 2023). "Some of the major genetic factors involved in immune response associated with uveitis include HLA genes and non-HLA genes such as CTLA-4, ILs, and KIR." (PMID 25097674, 2014). "In the current era of pharmacotherapy for uveitis, we can theoretically target TNF, IL-1, IL-12/IL-23, IL-6, IL-17, CTLA4, CD20, etc.—various cytokines that have been identified in the serum and eyes of patients with different types of uveitis." (PMID 31523783, 2019). "CTLA-4 blockade with abatacept reduced relapse rates by 38% in refractory noninfectious uveitis trials." (PMID 41268982, 2025). "Furthermore, our study also showed that anti-CTLA-4 and anti-PD1 combinatory regimes had the highest hazard ratio for uveitis development." (PMID 38264654, 2023). "Individuals who received monotherapy from the class of anti-PD-1 (HR:1.98 [CI: 1.65-2.37]) and anti-CTLA-4 (HR:5.86 [CI:1.99-17.24]) exhibited elevated hazard ratios for uveitis development compared to their non-ICI comparators." (PMID 38264654, 2023). "Those exposed to combinatory ICI regimens, specifically a combination of anti-PD-1 and anti-CTLA4 (HR: 5.04 [CI:3.55-7.16]), showed increased hazard ratios for uveitis development compared to their non-ICI comparators." (PMID 38264654, 2023). "Some of those genes have already been studied as potential therapeutic targets during EAU, e.g. Icos, IL17R or CTLA4 but numerous genes have not yet been explored in the field of uveitis." (PMID 32183784, 2020).
encephalitis (16 papers, 2019 to 2025). An acute inflammatory process affecting the brain parenchyma. "Although the incidence of encephalitis associated with PD-1/PD-L1 inhibitors (e.g., pembrolizumab) is lower than that of CTLA-4 inhibitors, its prognosis can be poor when it occurs." (PMID 40264768, 2025). "Anti-PD-1/PD-L1 therapy mostly leads to myasthenic syndromes, meningitis and cranial neuropathy, and rarely encephalitis and myositis; anti-CTLA-4 treatment mostly causes meningitis and less commonly encephalitis and myositis." (PMID 37304306, 2023). "Myasthenia and encephalitis are associated with anti-PD1 whereas other neurologic AEs such as meningitis or Guillain–Barré-like syndrome are associated with anti-CTLA-4." (PMID 33228219, 2020). "At 5 years following therapy initiation, patients receiving anti-PD-1/CTLA-4 combination immunotherapy exhibited significantly higher risk for immune-related meningitis (1.4% vs. 0.56%, OR: 2.6, 95% CI: [1.7,4.0]) and encephalitis (1.3% vs. 0.52%, OR: 2.5, 95% CI: [1.6, 3.9]) encounter diagnoses." (PMID 40351833, 2025). "Presently, it remains unknown which among the approved PD-1, PD-L1, or CTLA-4 inhibitors is primarily associated with causing encephalitis, given the scarcity of data related to the rarity of this adverse event." (PMID 38132400, 2023). "ICIs, including anti‐PD‐1 and anti‐CTLA‐4 agents, are increasingly recognized to induce various neuropsychiatric immune‐related adverse events, including encephalitis, aseptic meningitis, and, less frequently, delirium." (PMID 41220134, 2025). "In a large cohort of CTLA4 carriers, neurologic manifestations were reported in about one third of individuals, mainly encephalitis/encephalomyelitis, seizures, headache, and nausea." (PMID 40149457, 2025). "Additionally, a case of NMDA-R Ig encephalitis has been reported with combination PD-1 (nivolumab) and CTLA-4 (ipilimumab) therapy, however to our knowledge this is the first documented case of NMDA-R Ig encephalitis after single-agent pembrolizumab therapy." (PMID 31511075, 2019).
gastric adenocarcinoma (16 papers, 2016 to 2025). "One patient, with gastric adenocarcinoma, received anti‐CTLA4 tremelimumab combined with an OX40 agonist (clinical trial NCT02705482, described in)." (PMID 40769948, 2025). "Immunotherapy scores were constructed by the expression of PD-1 and CTLA4 in T cells of patients with gastric adenocarcinoma." (PMID 37251440, 2023). "It has been noted that immunotherapy, particularly anti-CTLA4 immunotherapy and 12 antigastric adenocarcinoma drugs, has resulted in a higher survival rate for patients with gastric adenocarcinoma." (PMID 37251440, 2023). "The expression of PD-1, PD-L1, and CTLA4 in gastric adenocarcinoma was all higher than in the normal group, with the expression levels of three common immune checkpoints distinctly upregulated in high-risk cohorts." (PMID 37251440, 2023). "The use of immune checkpoint inhibitors (ICIs), such as anti-PD-1, anti-CTLA4, and anti-PD-L1 antibodies, has demonstrated significant benefits in various cancers, including gastric adenocarcinomas." (PMID 33854974, 2021). "This study used IHC staining to assess the prognostic significance of PD-1, PD-L1, and CTLA-4 in gastric adenocarcinoma samples." (PMID 27741514, 2016). "We examined PD-L1 and CTLA-4 expression in tumor cells and CD8 and PD-1 expression in TILs in 464 cases of primary operable gastric adenocarcinoma using IHC analysis." (PMID 27741514, 2016). "Previous studies in stomach adenocarcinoma have similarly shown that dense ECM deposition can restrict T cell infiltration and interfere with the effectiveness of checkpoint blockade therapies, particularly those targeting PD1 and CTLA4." (PMID 41291892, 2025). "A randomized phase II (NCT03959293) study with a “stop and go” analysis is evaluating durvalumab with FOLFIRI (folinic acid (leucovorin) + fluorouracil + irinotecan) vs. tremelimumab (a fully human mAb against CTLA-4) and durvalumab with FOLFIRI for advanced gastric adenocarcinoma." (PMID 32679922, 2020). "Moreover, both CTLA4- and PD-1 positive and negative gastric adenocarcinomas with low expression of GPR176 had better responses to ICIs." (PMID 39711962, 2024).
dermatitis (15 papers, 2017 to 2024). An inflammatory process affecting the skin. "ICI-associated cutaneous disorders are the most prevalent effects induced in response to anti-programmed cell death 1 (PD-1), anti-cytotoxic T-lymphocyte-associated antigen-4 (CTLA-4), and anti-programmed cell death ligand 1 (PD-L1) agents." (PMID 39795946, 2024). "We report on the successful treatment of a severe, recalcitrant dermatitis caused by CTLA-4 insufficiency with dupilumab, raising the possibility of a role of type 2 immunity in clinical conditions associated with CTLA-4 insufficiency." (PMID 37780100, 2023). "An increase in miR155 levels maintained chronic skin inflammation through the modulation of CD4+ T cells and dendritic cells and the action on cytotoxic T-lymphocyte-associated antigen 4 (CTLA-4), which is a negative regulator of T lymphocyte activity." (PMID 37298095, 2023). "Overexpression of miR-155 decreases CTLA-4 levels and increases the proliferation of T-helper cells, promoting chronic skin inflammation." (PMID 37238937, 2023). "However, when the mice received concurrent cutaneous colonization with S. epidermidis and systemic anti-CTLA-4, skin inflammation developed on days 6 to 8 of treatment." (PMID 37298653, 2023). "As previously reported, miR-155 is significantly highly expressed in patients with AD and might result in chronic skin inflammation by elevating the proliferative response of T(H) cells via repression of CTLA-4." (PMID 35545774, 2022). "Treatment with anti-CTLA-4 alone did not produce any skin inflammation in the mouse model, nor did local skin colonization with Staphylococcus epidermidis." (PMID 37298653, 2023).
fibrosarcoma (15 papers, 2013 to 2025). A malignant mesenchymal fibroblastic neoplasm affecting the soft tissue and bone. "In addition, B. fragilis elicited Th1 immune responses and favored the maturation of intratumoral DCs, which potentiated the therapeutic efficacy of cytotoxic T lymphocyte-associated protein 4 (CTLA-4) blockade in fibrosarcoma-bearing mice." (PMID 37868956, 2023). "In a mouse model of fibrosarcoma, treatment with immune checkpoint inhibitors, (anti-PD-1 and -CTLA-4) induced the frequency and maturation of TA-HEVs and led to increased numbers of infiltrating CD4 and CD8 T cells." (PMID 38812785, 2024). "For LUR in combination with ICIs: anti-PD-L1 and anti-CTLA-4 showed strong anti-neoplastic effects in osteosarcoma and fibrosarcoma cell lines, and breast cancer and fibrosarcoma murine models." (PMID 38257245, 2024). "In this study, we demonstrated the potential of propranolol as a potent immune modulatory agent that can enhance the therapeutic efficacy of anti-CTLA4 checkpoint inhibitor therapy in STS using a murine fibrosarcoma model." (PMID 35017664, 2022). "In the presented studies, we describe preclinical evidence of synergy between CTLA-4 blockade and chemotherapeutic agents in various murine tumor models of fibrosarcoma and cancers of the mammary gland, lung, and colon." (PMID 23873089, 2013). "Notably, WDR75 showed the strongest association with rapidly accelerated fibrosarcoma (RAF), while DNTTIP2 and BRIX1 were most closely related to CTLA4." (PMID 40577282, 2025). "The mouse fibrosarcoma MCA205 progression has been shown to be controlled by cytotoxic T-lymphocyte-associated protein 4 (CTLA-4) antibodies in pathogen-free mouse but not in germ-free mouse." (PMID 33919907, 2021).
genitourinary cancers (15 papers, 2012 to 2025). "There are ongoing trials studying the use of a combination of anti-PD-1 and anti-CTLA-4 in rare Genitourinary cancers." (PMID 33080912, 2020). "The greatest risk of grade 3–4 PAEs in patients with urogenital cancer was related to anti-PDL1 plus targeted therapy drug, which had significant differences with the other interventions except for anti-PD1, anti-PD1 plus targeted therapy drug, and anti-PDL1 plus anti-CTLA4." (PMID 38373990, 2024).
lymphopenia (15 papers, 2015 to 2025). Reduction in the number of lymphocytes. "The mutations of CTLA4 are associated with lymphopenia and the reductions of tumor-infiltrating T cells, B cells, and natural killer (NK) cells." (PMID 36701414, 2023). "Utilizing key biomarkers such as low monocyte HLA-DR expression, persistent lymphocytopenia, and elevated PD-1/CTLA-4 for immune stratification is the core tool for selecting the correct timing and suitable patients." (PMID 41256846, 2025). "Patients with DEF6-mutation presented with CTLA-4 haploinsufficiency and LRBA deficiency including T cell lymphopenia, low class-switched B cells, hepatosplenomegaly, autoimmune hemolytic anemia, and bowel inflammation." (PMID 32566688, 2020). "ICIs (PD-1, TIM-3, CTLA-4) involved in inhibiting T-cell activation/proliferation of TIL-expressing solid tumors may lead to peripheral lymphopenia." (PMID 39141277, 2025). "Suppression of lymphopenia-driven expansion of Tconv cells is dependent on CTLA-4." (PMID 30856173, 2019). "An interesting aspect that merits consideration is the effect the induced lymphopenias might have on therapy designs where BRAFi are combined with immunotherapies such as CTLA-4 and PD-1 antibodies." (PMID 25897843, 2015). "Despite its major impact on survival, lymphopenia has not routinely been used to select candidates in anti-CTLA-4 and PD-1 immunotherapy protocols until recently." (PMID 30922400, 2019). "Simultaneously, lymphopenia reflects impaired cytotoxic immune surveillance, characterized by functional exhaustion of CD8+ T cells and natural killer cells through immune checkpoint axes such as PD-1/PD-L1 and CTLA-4, further reinforcing an immunosuppressive tumor niche." (PMID 41487591, 2025).
myositis (15 papers, 2021 to 2026). "Among the 26 ICI-related myositis, 11 events were caused by anti-PD-1, 13 by anti-programmed death ligand 1 (PD-L1), and two by anti-CTLA-4, suggesting that any ICI can elicit this condition." (PMID 34938300, 2021). "Both anti-PD-1/PD-L1 and anti-CTLA-4 antibodies can cause myositis, but anti-CTLA-4 antibodies have been reported less frequently and may cause myositis less frequently than treatment with anti-PD-1/PD-L1 antibodies." (PMID 34938300, 2021). "She started a treatment with Ipilimumab (Ipi, anti CTLA-4) and Nivolumab (Nivo, anti PD-1) and presented at day 10 a grade IV myositis mimicking bulbar palsy with dysphonia, dysarthria and aphagia." (PMID 39995675, 2025). "Immune checkpoint inhibitor therapy (ICI)-induced myositis (irMyositis) occurs in about 1% of patients treated with anti-PD1 or anti-CTLA-4 antibodies and can be debilitating or even fatal." (PMID 40759686, 2025). "The present study was is underpowered to determine differences in myositis-inducing effects of anti-CTLA-4 and PD-1/PD-L1 antibodies." (PMID 34938300, 2021). "While there is a case report of myositis associated with nivolumab, other reports of myositis have been noted in CTLA-4 blockade, which is not a drug used for bladder cancer." (PMID 35330111, 2022). "To address these gaps, we conducted a systematic review and meta-analysis to evaluate the risk of myositis associated with ICI for solid tumors by analyzing phase III randomized controlled trials of anti-programmed death-1/ligand-1 (PD-1/PD-L1) and anti-cytotoxic T-lymphocyte antigen-4 (CTLA-4)." (PMID 34938300, 2021). "In a murine C‐protein‐induced myositis (CIM) model, treatment with CTLA4‐Ig or anti‐CD80/86 antibodies effectively suppressed myositis, suggesting its potential therapeutic feasibility for myositis." (PMID 41371271, 2025). "The most common second-line therapy for refractory myositis was IVIG (when not offered initially) or abatacept, a CTLA-4 agonist." (PMID 36294298, 2022).
Addison’s disease (14 papers, 2005 to 2025). "Primary adrenal insufficiency is a very rare ICI-related endocrine complication, seen in 1.9% of patients on anti-CTLA-4/anti-PD-1 therapy and in 1% on monotherapies." (PMID 40860571, 2025).
graft versus host disease (14 papers, 2010 to 2024). An immune system disorder that occurs after allogeneic hematopoietic stem cell transplant and is a reaction of donor immune cells against host tissues. "Moreover, genetic polymorphisms in CTLA-4 and PD-1 genes have been also associated with the incidence of graft-versus-host disease after alloHSCT." (PMID 36742309, 2023). "Our study investigated the potential of peripheral blood T cell CD25, CD28, and CTLA-4 gene transcription levels as predictive biomarkers for acute graft-versus-host disease (aGVHD) following allogeneic hematopoietic stem cell transplantation (allo-HSCT)." (PMID 39072333, 2024). "Monogenic mutations affecting CTLA-4 or proteins in its pathway affect Treg function and antibodies that block activation of TGF-β by human Tregs prevent their ability to control xenogeneic graft-versus-host disease (GVHD)." (PMID 29163527, 2017). "But VIP can act directly on the Teff cells – culture of CD25−Foxp3− Teff with VIP induces their differentiation into CD25+Foxp3+ Treg that express high levels of IL-10 and CTLA4 and are protective in a mouse model of graft versus host disease (GVHD)." (PMID 24550907, 2014). "Additionally, using a mouse model of graft versus host disease (GVHD), anti-CTLA4-treated animals experienced less GVHD and a lower mortality rate than mice treated with anti-PD-1." (PMID 37760542, 2023). "For instance, the presence of susceptibility alleles at the 1722, 1661, and 318 promoter positions of CTLA-4 did not demonstrate a significant relationship with a graft versus host disease (GVHD) incidence, or disease recurrence." (PMID 25013611, 2011). "A promising approach in vivo for therapy of transplanted organ rejection and graft-versus-host disease (GVDH) is to efficiently kill alloreactive cells by selective depletion of T cells, targeting Cytotoxic T-lymphocyte Antigen-4 (CTLA4/CD152)." (PMID 22069572, 2010). "In contrast to anti–programmed cell death protein 1 (anti–PD-1) and anti–cytotoxic T lymphocyte–associated protein 4 (anti–CTLA-4) treatment, anti–TIM-3-treatment did not enhance acute graft-versus-host disease (aGVHD)." (PMID 38916965, 2024). "The anti-CTLA4 agent ipilimumab was explored in a phase I study on 12 R/R AML patients post ASCT; it allowed a complete response lasting greater than one year in five cases, despite reported immune-mediated toxic effects and graft versus host disease (GVHD)." (PMID 35409248, 2022).
heart failure (14 papers, 2017 to 2025). Inability of the heart to pump blood at an adequate rate to meet tissue metabolic requirements. "The percentages of CD4+CTLA-4+ T cells correlated strongly positively with the severity of heart failure New York Heart Association (NYHA) Functional Classification (Spearman’s rank correlation r = 0.7077, p < 0.001)." (PMID 36555549, 2022). "In iPAH patients, the percentages of CD4+CTLA-4+ T cells correlated strongly positively with the severity of heart failure New York Heart Association (NYHA) Functional Classification (r = 0.7077, p < 0.001)." (PMID 36555549, 2022). "Our findings indicate that disruption of PD-1 and CTLA-4 pathways exacerbates myocardial inflammation, accelerates atherosclerotic plaque formation, and promotes the development of heart failure." (PMID 40255399, 2025). "Similar outcome was reported in meta-analysis of 13346 subjects, 3.1% of the subjects receiving either CTLA-4 inhibitor or PD-1/L1 inhibitor and 5.8% of the subjects receiving combination therapy reported to have heart failure." (PMID 40255399, 2025). "Previous studies have demonstrated that PD-L1, PD-1, and CTLA-4 are important signaling pathways in cardiac immune crosstalk, and abrogation of those pathways leads to autoimmune myocarditis and heart failure." (PMID 36402980, 2022). "Of the 39 patients receiving two ICIs sequentially (PD-1/PD-L1 inhibitor + CTLA-4 inhibitor), five patients (12.8, 95% CI, 2.3–23.3) developed cardiomyopathy, and two patients (5.1, 95% CI, 0.0–12.1) developed heart failure." (PMID 33736707, 2021). "Recently, it has been demonstrated that blocking of T cell activation by abatacept, a cytotoxic T-lymphocyte-associated protein 4 (CTLA4)-Ig fusion protein, delays progression of TAC-induced heart failure." (PMID 30498501, 2018). "Researchers injected CTLA-4 antibodies into mice experiencing heart failure induced by transverse aortic constriction (TAC), confirming that CTLA-4 inhibition promotes CXCR4-mediated Th17 cell differentiation and activation, upregulating IL-17A production." (PMID 40821806, 2025). "In a more translational approach, we have used a molecule derived from Treg, CTLA-4, in soluble fusion protein form (CTLA-4-Ig/Abatacept) to treat advanced-stage heart failure in the pressure overload model." (PMID 32296427, 2020).